CD38 (CD38 molecule)
Diseases named in the same sentence as CD38 in open-access papers (continued):
Sharing a sentence is not in itself a finding about the gene and the disease.
cancer (continued). "Such cancer therapies include mAb-based therapies (using CD38-specific mAbs such as daratumumab and isatuximab), adoptive cell therapy (ACT) using CAR-Ts redirected against CD38, and radioimmunotherapy." (PMID 35468841, 2022). "There were eight favorable prognostic genes and six poor prognostic genes incorporated in this signature, and a variety of OSRGs such as CD38, FOXO1, HGF, IL18BP, and TRPM2 were closely involved in the previous studies regarding cancer subtypes and immune landscape." (PMID 36561981, 2022). "Indeed, subsequent reports have demonstrated that, for the subset of patients which express high levels of CD38, daratumumab treatment is able to inhibit NKTL survival and growth in both the cell lines and in a cancer xenograft model." (PMID 36139103, 2022). "This review focuses on targeting CD38 in cancer and non-cancerous diseases using antibodies, cell-based therapies and CD38 inhibitors." (PMID 36077708, 2022). "The review presents a comprehensive description of CD38’s application in the anticancer therapy and treatment of non-cancer diseases." (PMID 36077708, 2022). "In cancer, a crucial role of the CD38-NAD+ axis in T cells has also been suggested where reduced CD38 expression has been shown to correlate with higher cellular NAD+ levels, enhanced oxidative phosphorylation and glutaminolysis and improved T cell effector functions." (PMID 33790300, 2021). "CD38 is also found on the surface of erythrocytes and platelets, where it plays an essential role, together with platelet/endothelial cell adhesion molecule 1 (CD31), in the microenvironment retention of cancer cells." (PMID 33727923, 2021). "Next, we focused on the potential role of IL-33-responsive CD8Low and CD8High T lymphocytes during nutrient deprivation by analyzing cell surface markers such as the adenosine-converting ectoenzymes CD38 and CD39, which have been proposed as targets for cancer immunotherapy." (PMID 34504486, 2021). "Hence, our comprehensive and systematic analysis study provides valuable insights into the potential immune regulatory role of CD38 in the EOC niche and suggests its use as a cancer prognostic biomarker." (PMID 32425977, 2020). "CD38 is an ectoenzyme that, by consuming extracellular NAD, leads to mitochondrial dysfunction of surrounding cells, as observed in metabolic diseases and cancer." (PMID 31130949, 2019). "The inhibition of angiogenesis is a potential treatment modality for cancer, and this may be achieved through the inhibition of NAADP production by CD38." (PMID 31861847, 2019). "Nevertheless, although our findings indicate that CD38 acts via different TME cells in different tissues and cancer types, it may still act via common pathway(s) e.g., increased NAD+ levels and/or reduced CD38 metabolites levels e.g., NAADP." (PMID 30159123, 2018). "However, the interest in ADO and ectoenzymes involved in ADO formation (CD38, CD39, CD73 and CD203a) was prompted by growing evidence of their role in cancer biology." (PMID 29731713, 2018). "Moreover, in addition to Lin28B there are several putative cancer stem cell markers, such as MUC1, CD38, FLOT2, EGF and IKBKB that were also upregulated (signal log2 ratio>0.5) in mH2A1-depleted LD611 cells." (PMID 26028027, 2016). "We demonstrate that a potent small molecule inhibitor of the NKA can be covalently attached to antibodies targeting CD20, CD38, CD56, CD147, or dysadherin, to create a series of selective and powerful EDCs that kill cancer cells extracellularly by a mechanism resembling necrosis." (PMID 27434591, 2016). "Moreover, CD38 expression has gained importance as a prognostic marker in chronic lymphocytic leukemia (CLL), HIV infection and cancer." (PMID 23946809, 2013). "Although c-Myc was not differentially expressed between high- and low-CD38 subgroups, it was included in our study because: it is a transcription factor that plays a critical role in certain cancers." (PMID 23936412, 2013).
cancer (continued). "Whether AL with low or negative CD38 expression can benefit from daratumumab treatment warrants further investigation as this antibody not only targets cancer directly but also promotes an antitumor immune response." (PMID 39046511, 2024). "Furthermore, the novel link between MDSCs and up-regulated expression of CD38 and KLRG1 on T cells and NK cells identified in this study suggests a wider scope of applications for CD38- and KLRG1-blocking drugs in immunotherapies of cancers and inflammatory diseases." (PMID 37207205, 2023). "Since the high concentration of extracellular NAD+ is present in the TME niche in some cancer types, probably due in part to the altered metabolism in cancer cells, the non-classical eADO production pathway mediated by CD38 also plays an influential role in eADO signaling in several solid tumors." (PMID 36911717, 2023). "The promoter region of CD38 is atypical, lacking a canonical TATA box but containing a CpG island, thereby suggesting susceptibility to epigenetic modulators, which has been increasingly observed in cancer studies." (PMID 36139103, 2022). "CD38 plays an important role in cancer and non-cancerous diseases." (PMID 36077708, 2022). "Interestingly, in cancers that show resistance to PD1 inhibitor, CD38 expression is upregulated in exhausted CD8 T cell populations, but a critical role of CD38-mediated NAD+ depletion in resistance to PD1 inhibitor cancer therapy needs further investigation." (PMID 35801078, 2022). "Therefore, cells overexpressing CD38 in the TME direct the generation of an immune suppressive environment that reduces effector T cell functions but also promotes angiogenesis provides immune escape and helps in cancer progression." (PMID 33727923, 2021). "Bearing that in mind, targeting CD38 in other nonhematological cancer types, especially carcinomas, which are of epithelial origin with specific anti-CD38 antibodies alone or in combination with immunomodulatory drugs, is an interesting option that deserves profound consideration." (PMID 33727923, 2021). "Flavonoid CD38 inhibitors demonstrate a lack of toxicity in humans and beneficial effects in animal models of obesity, heart ischemia, kidney injury, viral infection, and cancer." (PMID 31214171, 2019). "Although these studies separately showed elevated expressions of CD38 and NGAL-R, it is very likely that both antigens are co-expressed in these tumors, and therefore suggest that a combination of anti-CD38/NGAL-R Abs may offer new therapeutic options for the management of these cancers." (PMID 37760777, 2023). "Additionally, CD38 increases the phosphorylation of PI3K, AKT, and mTORC and upregulates the PI3K/AKT/mTOR pathway, which is related to metabolic reprogramming and proliferation of cancer cells, while such effects were significantly reversed with mTOR inhibitor, rapamycin." (PMID 33727923, 2021). "All together these evidences suggest the existence of a vicious cycle between CD38/ADO and PD-1/PD-L1 axis in cancers; however, this approach has not been explored in depth in MM patients." (PMID 33418913, 2021). "As opposed to reported findings in AML, we showed that cancer stem cells from MDS samples derived from both CLEC12A positive and negative CD34+CD38− subpopulations." (PMID 27612176, 2016).
hematological malignancies (65 papers, 2015 to 2026). "Anti-CD38 antibodies exhibited strong ADCC activity against cells associated with hematological malignancies (Daudi, L-1236, Raji, and NCI-H929 cell lines) in a concentration-dependent manner via FcR-TANK (effector)." (PMID 38983860, 2024). "High expression of CD38 has often been found to be associated with several hematological malignancies." (PMID 32709019, 2020). "The goal of this study was to generate nanobodies directed against the cell surface ecto-enzyme CD38 as new diagnostic and potential therapeutic tools for hematological malignancies." (PMID 29084989, 2017). "CD38 is important for the regulation of hematopoiesis, and its downregulation in bone marrow precursor cells could disrupt this process, potentially leading to deficiencies in certain blood cell lineages and contributing to hematological disorders such as MDN." (PMID 40568578, 2025). "We believe that CD38 represents a valuable, broadly applicable target, and that a universal CD38-targeting CAR construct holds promise for treating various hematologic malignancies." (PMID 39856752, 2025). "Although this study focused on the role of CD38 in aging and related diseases, the keyword co-occurrence and clustering analysis highlighted hematological disorders as the dominant research area." (PMID 40529366, 2025). "It has been extensively studied in neuroendocrine tumors and prostate cancer, but recent research suggests its potential in CD38-targeted therapy for hematological malignancies." (PMID 40227793, 2025). "This study reveals characteristics of CD38 antibody resistant CTCL cells in vivo, emphasizing the therapy’s promise in conditions with elevated CD38 expression, such as hematological malignancies." (PMID 40057636, 2025). "This approach increased CDC function in MM cells (even in cells expressing low levels of surface CD38) and was also effective against other hematological malignancies." (PMID 40013150, 2025). "Preclinical studies and clinical trials evaluating CD38 inhibition are ongoing in patients with either solid tumors or hematological malignancies, including MM." (PMID 40013150, 2025). "Our study highlights the transformative potential of allogeneic CD38-targeting universal CAR-T cell therapy for hematological malignancies." (PMID 39856752, 2025). "To summarize, we reported a novel strategy for treating hematologic malignancies that are CD38-positive by simultaneously targeting CD47 and CD38 via a first-in-class bispecific antibody." (PMID 38983860, 2024). "Here we described ISB 1442, a fit-for-purpose multispecific antibody, rationally designed to harness innate immunity to treat CD38+ hematologic malignancies." (PMID 38448430, 2024). "Here we report the development of ISB 1442, a fully human bispecific antibody designed to re-establish synthetic immunity in CD38+ hematological malignancies." (PMID 38448430, 2024). "Initial practices of anti-CD38 therapies targeted against hematologic malignancies, a highly heterogeneous group of diseases that originate in the blood, bone marrow, and lymphatic system." (PMID 38765013, 2024). "Isatuximab (Isa) is an IgG1 monoclonal antibody that targets a specific epitope on CD38 and kills CD38+ cells from hematological malignancies via multiple mechanisms." (PMID 36251503, 2023). "Many preclinical studies and clinical trials evaluating CD38 inhibition are ongoing or have been completed with patients harboring either hematological malignancies or solid tumors." (PMID 38116009, 2023). "This will highlight potential strategies that can be utilized in combination with CD38-targeting antibodies to enhance therapeutic responses in CD38-driven hematologic malignancies." (PMID 36139103, 2022). "It is currently being evaluated in CD38-positive hematological malignancies for its efficacy and safety." (PMID 36313735, 2022). "In other hematological malignancies, the clinical evaluation of CD38-targeting antibodies is still in its early stages." (PMID 36139103, 2022).
hematological malignancies (continued). "CD 38 is a therapeutic target for many different hematological malignancies and there is a comprehensive list of monoclonal antibodies directed against the CD38 have been produced and approved." (PMID 33794925, 2021). "Targeting CD38 with anti-CD38 monoclonal antibodies in hematological malignancies has shown excellent results." (PMID 33727923, 2021). "We believe that such an agent will show widely applicable clinical utility in many types of CD38‐positive hematological diseases." (PMID 34026426, 2021). "Among the identified seven genes (LRRC17, ZHX3, CD38, AKR1B10, LYPD6B, KIAA2022, and CMBL) in our study, CD38 was well known about its correlation with hematological malignancies." (PMID 31856408, 2020). "Owing to high CD38 expression, therapeutic interventions targeting CD38 are being devised for various hematological malignancies." (PMID 32709019, 2020). "Our results underscore the potential of hcAbs for therapy of CD38-expressing hematological malignancies." (PMID 32194826, 2020). "Abnormal CD38 expression in hematologic malignancies correlates with cellular proliferation and disease progression, thus making CD38 an attractive target for antibody-based therapeutics." (PMID 32225002, 2020). "Our goal was to evaluate the potential of CD38-specific nanobodies as novel diagnostics for hematological malignancies." (PMID 29084989, 2017). "Our aim was to evaluate the potential of CD38-specific nanobodies as novel diagnostics for hematological malignancies." (PMID 29084989, 2017). "CD38 is a 43 kDa type II transmembrane ecto-enzyme that is highly expressed in hematological malignancies including multiple myeloma." (PMID 29084989, 2017). "This could be due to the larger volume of studies exploring the role of CD38 in hematological diseases compared to age-related diseases." (PMID 40529366, 2025). "The protumorigenic function of CD38 in hematologic malignancies has been extensively investigated." (PMID 40382743, 2025). "Inhibitors of CD38, such as daratumumab, have been successfully used in hematological malignancies and may have potential in modulating B cell-driven inflammation in AKI." (PMID 41844385, 2025). "Notably, the CD markers CD56 and CD38, commonly used in identifying blood cell populations, have proven valuable in diagnosing and treating blood disorders." (PMID 39559206, 2024). "Indeed, many preclinical studies and clinical trials to evaluate CD38 inhibition in both solid tumors and hematological malignancies are ongoing or have been completed." (PMID 38116009, 2023). "Key clinical studies of CD38-targeting antibodies in hematological malignancies." (PMID 36139103, 2022). "Thus, CD38 is an attractive and novel target, especially in highly aggressive hematologic malignancies for which novel treatment modalities are scarce." (PMID 36139103, 2022). "The cluster of differentiation 38 (CD38) protein is a enzyme with multiple functions including degrading nicotinamide adenine dinucleotide (NAD) and regulating cellular NAD homeostasis; it has been discovered that CD38 was a cell surface marker of hematological malignancies such as MM." (PMID 34488679, 2021). "Ongoing pre-clinical validation studies will determine if this method could be utilized across a wide range of CD38 expressing hematologic malignancies." (PMID 33766099, 2021). "While the role of CD38 in hematological malignancies has been extensively studied, the impact of CD38 expression within solid tumors is largely unknown, though most current data indicate an immunosuppressive role for CD38." (PMID 31878283, 2019). "In conclusion, these studies indicate that CD38 is crucial for cell-mediated immuno-modulatory functions and pro-tumoral interactions with components of the microenvironment, thus supporting the use of monoclonal antibodies for the treatment of hematological and non-hematological malignancies." (PMID 32225002, 2020).
hematological malignancies (continued). "Targets of BsAbs developed for hematological malignancies, including CD19, CD20, CD33, CD38 (also known as ADPRC1), CD123, and B-cell maturation antigen (BCMA, also known as TNFRSF17), are commonly expressed on normal B and plasma cells." (PMID 40565299, 2025). "In hematologic malignancies, rituximab (anti-CD20) and daratumumab (anti-CD38) are NK-cell-dependent antibodies that are widely utilized for B cell malignancies and MM, respectively." (PMID 33766099, 2021). "Additional CAR NK cell targets being developed for hematologic malignancies include CD33, CD38, CD123, CD20, BCMA, CLL1, and FLT3, and dual-target CARs such as CD19/20 or CD19/22." (PMID 33766099, 2021). "Immunotherapies with mAbs specific to CD19, CD20, CD22, CD38, as well as chimeric antigen receptor (CAR)-modified T cell therapy, have recently revolutionized the treatment of hematological malignancies." (PMID 32806528, 2020). "At variance with CD38, CD157 presents a more restricted pattern of expression in hematological malignancies, being present only in B-ALL and AML, where it serves as target for selective monoclonal antibodies." (PMID 31636635, 2019). "Most monoclonal antibodies used in hematologic malignancies, such as rituximab (anti-CD20), alemtuzumab (anti-CD52), and daratumumab (anti-CD38), are not commonly associated with direct ocular toxicities." (PMID 41568391, 2025). "In hematologic malignancies, anti-CD20, anti-CD19, anti-CD38, and anti–B-cell maturation antigen (BCMA) antibodies have markedly improved survival outcomes, whereas antibody–drug conjugates and bispecific antibodies continue to expand therapeutic possibilities." (PMID 41511330, 2025). "We also discuss the basic research and ongoing clinical trials on emerging immune checkpoints (Galectin-9/Tim-3, CD70/CD27, LAG-3, and LILRBs) and on new targets for CAR-T cell therapy (CD22, CD33, CD123, BCMA, CD38, and CD138) for the treatment of hematologic malignancies." (PMID 31186046, 2019). "However, specific data on immune responses to booster vaccinations, particularly in patients with hematologic malignancies undergoing active chemotherapy, as well as anti-CD38 or anti-BCMA regimens, are lacking." (PMID 37509261, 2023). "Moreover, the concept of sTRAIL fusion may also be applicable to antibodies targeting other important antigens in hematological malignancies such as CD20 and CD38 for which TRAIL fusion constructs were already described or further novel targets such as CD52 and CD79." (PMID 34203833, 2021).